H2AL1Q (H2A.L variant histone 1Q)
Synonyms: H2A.L.1; formerly H2AL1QP
Gene: Protein-coding gene on chromosome X (36,719,829 to 36,720,573, forward strand). Ensembl gene ENSG00000249467.
Gene Ontology:
Molecular function: structural constituent of chromatin; DNA binding; protein heterodimerization activity
Biological process: heterochromatin formation
Cellular component: nucleosome; nucleus
Homologues: Orthologues: dog H2AL1Q (34% identical), mouse H2al2a (29% identical), mouse H2al2b (26% identical), mouse H2al2c (26% identical), rat H2al3 (25% identical), mouse H2al1n (24% identical), mouse H2al1a (24% identical), mouse H2al1b (24% identical), mouse H2al1c (24% identical), mouse H2al1d (24% identical), mouse H2al1e (24% identical), mouse H2al1f (24% identical), and 27 more. Paralogues in human: H2AL3 (53% identical), H2AB2 (26% identical), H2AB3 (26% identical), H2AB1 (26% identical), MACROH2A2 (26% identical), MACROH2A1 (25% identical), H2AC21 (24% identical), H2AC6 (24% identical), H2AJ (24% identical), H2AX (24% identical), H2AC1 (24% identical), H2AC11 (24% identical), and 15 more.
Diseases named in the same sentence as H2AL1Q in open-access papers:
H2AL1Q is named in the same sentence as 1 disease in open-access papers, as found by Europe PMC text mining. Sharing a sentence is not in itself a finding about the gene and the disease.
H2AL1Q shares sentences with these, for which no sentence is quoted: male infertility (1 paper).